FGFBP2 (fibroblast growth factor binding protein 2)
Synonyms: Ksp37; HBP17RP
Tractability: Antibody: UniProt places it where antibodies can reach, with high confidence; UniProt predicts a signal peptide or a membrane-spanning region; its Gene Ontology location is reachable by antibodies, with medium confidence. PROTAC: its protein half-life has been measured.
Gene: Protein-coding gene on chromosome 4 (15,960,245 to 15,969,309, reverse strand). Ensembl gene ENSG00000137441.
Subcellular location: Secreted, extracellular space
Pathways (Reactome):
Signal Transduction: FGFR2b ligand binding and activation
Gene Ontology:
Molecular function: protein binding; growth factor binding
Biological process: cell-cell signaling
Cellular component: extracellular region
Genetic constraint (gnomAD): Loss-of-function variants: 7 observed, 6.58 expected, observed/expected ratio (o/e) 1.06, 90% interval 0.6 to 1.8. That is too few expected variants to judge how well the gene tolerates losing a copy. Missense variants: 291 observed, 275.87 expected, observed/expected ratio (o/e) 1.05, 90% interval 0.96 to 1.16. Synonymous variants: 131 observed, 109.19 expected, observed/expected ratio (o/e) 1.2, 90% interval 1.04 to 1.39.
Homologues: Orthologues: chimpanzee FGFBP2 (99% identical), macaque FGFBP2 (93% identical), rabbit FGFBP2 (61% identical), zebrafish fgfbp2b (28% identical), tropical clawed frog fgfbp2 (25% identical), zebrafish fgfbp2a (24% identical). Paralogues in human: FGFBP1 (19% identical), FGFBP3 (19% identical).
Diseases named in the same sentence as FGFBP2 in open-access papers:
FGFBP2 is named in the same sentence as 21 diseases in open-access papers, as found by Europe PMC text mining. Sharing a sentence is not in itself a finding about the gene and the disease. The quoted sentences say what the papers report.
breast carcinoma (2 papers, 2011 to 2025). "To this end, we completed multiplex immunohistochemistry (mIHC) on primary tumour tissues from 6 non-metastatic early breast cancer (EBC) and 4 metastatic breast cancer (MBC) patients to determine the relative proportion of FGFBP2+ γδ T cells between these two conditions." (PMID 40340807, 2025).
dementia (2 papers, 2023). Loss of intellectual abilities interfering with an individual's social and occupational functions. "The gene encoding for fibroblast growth factor binding protein 2 (FGFBP2) was found to be more highly expressed in the MCI group compared to the CN group (P-value = 0.048) and dementia group (P-value = 0.018)." (PMID 37066364, 2023). "Four genes (FGFBP2, PRSS23, TGFBR3, NUAK1) out of the 5 top IL-7Rαlow aging genes remained differentially expressed with decreased relative gene expression in the dementia group compared to the MCI group." (PMID 38042785, 2023). "Four genes (FGFBP2, PRSS23, TGFBR3, NUAK1) out of 5 top IL-7Rαlow aging genes remained differentially expressed at the P < 0.05 significance level after Šidák correction with decreased relative gene expression in the dementia group compared to the MCI group." (PMID 37066364, 2023).
melanoma (2 papers, 2023 to 2024). A malignant, usually aggressive tumor composed of atypical, neoplastic melanocytes. "Notably, we identify a strong association between MYC+ Melanoma (MYC+MEL) and FGFBP2+NKT cells with LN metastasis." (PMID 38065972, 2023). "The MYC+ Melanoma (MYC+MEL) and FGFBP2+NKT subclusters are tightly correlated with LN metastasis and poor prognosis." (PMID 38065972, 2023).
ankylosing spondylitis (1 paper, 2025). An autoimmune chronic inflammatory disorder characterized by inflammation in the vertebral joints of the spine and sacroiliac joints. "Some researchers have identified FGFBP2 as a key gene involved in NK cell-mediated immune response in ankylosing spondylitis." (PMID 40416605, 2025).
autoimmune disorders (1 paper, 2024). "Our analysis indicated that both subsets showed enhanced cytotoxicity, with sustained increases in expression and chromatin accessibility of key cytotoxic genes such as GZMB, FGFBP2, CTSW, PRF1, which are crucial in other autoimmune disorders." (PMID 39365735, 2024).
chordoma (1 paper, 2022). Chordomas are rare malignant tumors arising from embryonic remnants of the notochord in axial skeleton. "Additionally, BATF, ACTR3C, and FGFBP2 have been implicated in cancers other than chordomas." (PMID 36439461, 2022).
keloid (1 paper, 2025). An irregularly shaped, elevated mark on the skin caused by deposits of excessive amounts of collagen during wound healing. "IGFBP2+ fibs are distinguished by the expression of marker genes including IGFBP2, FGFBP2, OLFML2A, CPE, APOD, and SLC7A2, which are markedly upregulated in normal skin tissue relative to keloid tissue." (PMID 39902627, 2025). "We then focused on comparing the expression differences of IGFBP2+ fib marker genes (IGFBP2, FGFBP2, OLFML2A, CPE, APOD, SLC7A2) between keloids and normal controls." (PMID 39902627, 2025).
Megalencephalic leukoencephalopathy (1 paper, 2019). "We also observed only three overlapping genes between differentially expressed genes in these three selected modules: FGFBP2, GFOD1, MLC1, which were functionally enriched for revascularization, glycometabolism, Megalencephalic leukoencephalopathy with subcortical cysts pathways." (PMID 30683112, 2019).
Sepsis (1 paper, 2025). Sepsis is defined as life-threatening organ dysfunction caused by a dysregulated host response to infection. "sc-RNA seq and assignment into two types of NK cells confirmed that heatstroke and sepsis were associated with lower number of NK cells than that in the other two groups, rather than affecting the relative abundance of CD56bri NK cells (NKG7+XCL1+) and CD56dim NK cells (NKG7+FGFBP2+)." (PMID 40084252, 2025).
tumor (21 papers, 2018 to 2025). "New clonotypes appearing in blood or tumor at disease progression were enriched for genes associated with cytotoxicity or stemness (FGFBP2, GNLY, GZMH, GZMK, IL7R, SELL and KLF2), and these might be harnessed for alternative cellular therapy or cytokine therapy." (PMID 36514045, 2022). "Upregulated EOMES and TNFSFR9 and downregulated genes (PAG1, GNLY, ANXA1, FGFBP2) that are involved in tumor escape from immune surveillance by suppressing T-cells or by reprogramming T-cells toward T-cell exhaustion." (PMID 40079005, 2025). "In contrary we found upregulated (EOMES, TNFSFR9, TIGIT, KLRD1) and downregulated genes (PAG1, GNLY, ANXA1, FGFBP2) that are involved in tumor escape from immune surveillance by suppressing T-cells or by reprogramming T-cells toward T-cell exhaustion." (PMID 40079005, 2025). "Our results demonstrated that FGFBP2+ NK cells in tumor tissues exhibited a functionally inhibited state due to overexpression of HAVCR2." (PMID 38604154, 2024). "Unsurprisingly, these genes have been previously associated with tumor growth and metastasis (NUAK1, TGFBR3, FGFBP2), as well as autoimmune disorders (PRSS23)." (PMID 37066364, 2023). "Accordingly, FGFBP2+NKT cells expressed the highest levels of cytotoxic genes, such as GZMB, GZMH, PRF1, and GNLY, indicating that FGFBP2+NKT cells had the strongest tumor-killing effects." (PMID 38065972, 2023). "Owing to the potent anti-tumor ability, we further investigated the relationship between FGFBP2+NKT cells and LN metastasis in AM." (PMID 38065972, 2023). "These genes have been previously associated with tumor growth and metastasis (NUAK1, TGFBR3, FGFBP2), as well as autoimmune disorders (PRSS23)." (PMID 38042785, 2023). "As demonstrated by our results, FGFBP2+ NK cells expressed the highest level of killing-related genes, suggesting that it might play a tumor cell killing role in the immune microenvironment." (PMID 38604154, 2024). "Notably, our in-depth analysis revealed that these FGFBP2+NKT cells possessed the strongest tumor-killing ability within the AM ecosystem." (PMID 38065972, 2023). "According to the statistical results, the proportions of FGFBP2+ NK cells, IL1RL1+ T cells, CTLA4+ T cells, Myeloid cells 1, and Plasma B cells were higher than that of normal in tumor tissues." (PMID 38604154, 2024). "While in detail, exhausted CD8+T and CD4+T cells were increased, and XCL2+NK and FGFBP2+NKT cells were decreased in LN+AM compared to those in LN−AM, indicating a compromised anti-tumor TME." (PMID 38065972, 2023). "CD8-05-FGFBP2 cluster exhibited a CD8+ effector phenotype, upregulating genes involved in cytotoxicity and anti-tumor activity: FGFBP2, GNLY, FCGR3A, GZMH, PRF1, TGFBR3, and GZMB." (PMID 36350695, 2022). "Expression of membrane receptors such as FCGR3A and CX3CR1, and cytotoxic genes like GZMB, FGFBP2, PRF1, and GNLY increased gradually during this transition, implying a gradually acquired tumor-killing ability in CD56dim NK cells." (PMID 33298893, 2020). "In addition, we found a higher proportion of FGFBP2+ NK cells, CTLA4+ T cells, and a lower proportion of LAG3+ T cells in tumor tissues compared to normal tissues." (PMID 38604154, 2024). "Similarly, FGFBP2+ NK cells also highly expressed markers like GNLY, NKG7, and PRF1, indicating a strong anti-tumor immune response." (PMID 39093451, 2024). "Recent single-cell transcriptome sequencing studies on HCC have confirmed that different immune cells express different PANoptosis-related genes (CRADD is upregulated in tumor-specific infiltrating regulatory T cells; TNF is upregulated in cytotoxic FGFBP2+ double‐positive T cells)." (PMID 37662906, 2023). "Using multiplex IHC assays, we showed that FGFBP2+NKT cells (positive for CD8, NCAM1, and FGFBP2, but not for CD4) were mainly present in the para-tumor regions and were sparsely distributed in the tumor regions." (PMID 38065972, 2023).
tumor (continued). "In the comparison of differentially expressed genes (DEGs) between LUAD and normal tissues, three genes (FGFBP2, CRIP1, and PRF1) were mainly expressed in normal tissues but not in tumor-derived cells." (PMID 36483553, 2022).
cancer (5 papers, 2010 to 2025). A tumor composed of atypical neoplastic, often pleomorphic cells that invade other tissues. "FGFBP2 showed six- to eightfold higher levels in clear cell stage I carcinomas compared with the more advanced staged carcinomas and correlated positively with an improved clinical outcome." (PMID 36439461, 2022).
FGFBP2 also shares sentences with these, for which no sentence is quoted: anaplastic large cell lymphoma (1 paper); bladder cancer (1); chronic pancreatitis (1); glioma (1); Graves disease (1); hepatocellular carcinoma (1); leukemia (1); lymphoma (1); metastatic disease (1); myopathy (1).